BRAF (B-Raf proto-oncogene, serine/threonine kinase)
Diseases named in the same sentence as BRAF in open-access papers (continued):
Sharing a sentence is not in itself a finding about the gene and the disease.
melanoma (continued). "Here we tested the ability of HGF to rescue cells from dabrafenib, a selective BRAF inhibitor, approved for the treatment of BRAFV600E mutant melanoma, with similar clinical efficacy as vemurafenib but a differentiated safety profile." (PMID 28147313, 2017). "bFGF was identified as an autocrine growth factor for melanoma, and blockage of FGFR synergistically enhances effects of BRAF inhibition in melanoma cells." (PMID 28829835, 2017). "As neurofibromin activity is a key to regulating the RAS/MAPK pathway, NF1 mutations are important in the acquisition of drug resistance, to BRAF, EGFR inhibitors, tamoxifen and retinoic acid in melanoma, lung and breast cancers and neuroblastoma." (PMID 28637487, 2017). "Owing to the propensity of MEK to evolve an array of activating mutations, our results support the co-targeting of alternative MAPK pathway members in conjunction with BRAF inhibitors for patients with high-grade, BRAFV600E-driven melanoma." (PMID 28263969, 2017). "In the last five years, the introduction of several novel targeted therapies, including BRAF inhibitors, MEK inhibitors, and immunotherapies, has dramatically improved patient outcomes in advanced melanoma." (PMID 28895885, 2017). "Besides a specific anti-melanoma effect, however, targeted agents may potentially restore the immune system activity and early studies proved that inhibition of BRAF cascade raises the number of CD8+ T-cells nearby tumor cells and increases the exposition of TAAs synthesized by melanoma cells." (PMID 29285320, 2017). "Following the approval of BRAF/MEK inhibitors and PD-1/CTLA-4 blocking antibodies starting in 2011, the use of HD IL-2 in the frontline therapy of melanoma gradually declined." (PMID 28923120, 2017). "First, we substituted the selective BRAF inhibitor Dabrafenib for the MEK inhibitor Trametinib and tested it in combination with Everolimus in M14 and WM115 melanoma cells." (PMID 28220839, 2017). "Taken together, these results show that RAF signalling is absolutely required downstream of NRAS, and disclose both specific and compensatory functions for BRAF and CRAF kinases in NRAS-induced mouse melanoma." (PMID 28497782, 2017). "Due to its downstream signaling to the MAPK pathway and the knowledge that BRAF inhibitors lead to enhanced growth of BRAFwt melanomas, several trials investigated the efficiency of MEK inhibition in this subset of melanoma." (PMID 28350340, 2017). "More recently, combination therapy of BRAF and MEK inhibitors has improved response rates to approximately 70% in patients with BRAFV600E mutant melanoma while exhibiting evidence of clinical benefit in almost all patients." (PMID 28147313, 2017). "To investigate how HDACis affected PMCA expression in melanoma cells, we treated one BRAF wild-type (MEWO) and two BRAF-mutant (A375, A2058) cell lines either with increasing concentrations of SAHA or valproate or for different time intervals." (PMID 28596940, 2017). "Combination with BRAF and EZH2 inhibition showed better inhibitory efficacy in melanoma prevention compared with vemurafenib monotherapy." (PMID 29202777, 2017). "Finally and also consistent with our data, the already mentioned study regarding the EGFR‐induced slow‐growth phenotype of BRAFV600 melanoma cells that may foster the emergence of resistance cells, compared to fast‐proliferating cells, under prolonged BRAF inhibition." (PMID 28573821, 2017). "Aside from clinical efficacy, BRAF and MEK inhibition leads to increased melanoma neoantigen expression, paradoxical activation of MAPK signaling on T lymphocytes, PD-L1 expression upregulation, and inhibition of suppressive cytokines." (PMID 28848761, 2017).
melanoma (continued). "The effect of BRAF/MEK inhibitors on the expression of CD47 was confirmed in additional two BRAFV600E (IgR3 and Sk-Mel-28) and two wild-type BRAF (ME1007 and ME4405) melanoma cells lines treated with vemurafenib and trametinib, respectively." (PMID 29050218, 2017). "More specifically, resistance to small-molecule BRAF and MEK kinase inhibitors has been well-documented as limiting the efficacy of these agents in BRAFV600E mutant melanoma." (PMID 28147313, 2017). "In malignant melanoma, a FDA approved selective BRAF inhibitor vemurafenib (PLX4032) has shown high treatment response." (PMID 27880942, 2017). "Similar selectivity and efficacy of trametinib was also reported as a single-agent in wild-type BRAF/NRAS, NF1-altered melanomas." (PMID 29156677, 2017). "The anti-CSPG4 mAb 225.28 combined with a BRAF inhibitor exhibited synergistic antitumor effects and enhanced efficacy against BRAFV600E mutant melanoma cells in vitro compared to either agent alone." (PMID 29375561, 2017). "This evidence is consistent with previous studies, in colon carcinoma and melanoma cells, suggesting that EGFR expression dictates the activity of BRAF inhibitors." (PMID 29033690, 2017). "Approximately half of all human BRAF mutant melanoma tumors express high levels of RhoJ, identifying the RhoJ-BAD pathway as a novel target for melanoma." (PMID 28753606, 2017). "The introduction of BRAF/MEK inhibitor combinations has yielded significant increases in PFS and OS for melanoma." (PMID 28052762, 2017). "PKRCA binds with BRAF, but it is mechanistically unclear how PKRCA activation would result in treatment of melanoma." (PMID 37133296, 2017). "Seven miRNAs, which were reduced by BRAF/MAPK signaling pathway, such as let-7i, miR-34a and miR-22 effectively inhibited melanoma cell proliferation." (PMID 28118616, 2017). "In line with this, we have previously shown that combined inhibition of BRAF and FGFR1 has synergistic anti-melanoma effects." (PMID 29152117, 2017). "MEK1/2 inhibitors such as trametinib have been shown to be active in BRAF/NRAS wild type melanomas and induced at least a partial response in 10% of melanoma patients." (PMID 27903987, 2017). "The MAP‐kinase (MAPK) pathway is deregulated in the majority of malignant melanomas, and targeting the primary driver of hyper‐active MAPK signalling, BRAF shows impressive initial responses in patients." (PMID 28606996, 2017). "BRAF-activated BANCR has been shown to promote cell migration and proliferation in melanoma and lung carcinoma via the MAPK signaling pathway." (PMID 27462868, 2017). "Despite the spectacular achievements of targeted therapies (BRAF inhibitors) or immuno-therapies (anti-CTLA4 or anti-PD1), most patients with melanoma will need additional treatments." (PMID 27756874, 2016). "BRAF wild-type (WM1366 and MeWo) human melanoma tumor cell lines were used and cells were plated at a density of 3 × 104 cells/well in 96 well plates." (PMID 27783987, 2016). "In 2011, the United States Food and Drug Association approved two new treatments for advanced, unresectable melanoma - the antagonist cytotoxic T-lymphocyte antigen 4 (CTLA-4) antibody, ipilimumab, and the targeted BRAF inhibitor, vemurafenib." (PMID 27777775, 2016). "Resistance to BRAF and MEK inhibitors can be mediated by activation of the PI3K pathway, providing a strong rationale for combination therapy in melanoma." (PMID 27047798, 2016). "Other studies have shown that BRAF inhibition induces PI3K/AKT activation and that PI3K/mTOR inhibitors enhances the anti-melanoma activity of BRAF and MEK inhibitors in vivo." (PMID 27655717, 2016). "NK cells, cultured with IL-2, IL-15 or IL-15/IL-18 and in the presence of either BRAF-i or MEK-i, were analyzed for their ability to kill different melanoma cell lines including MeCoP, MeTA, MeDeBO and FO-1." (PMID 27563819, 2016).
melanoma (continued). "Treatment with a combination of a BRAF- and MEK inhibitor results in a high tumor response rate (64–69 %) and improves the survival of patients with BRAF V600 mutant melanoma." (PMID 27095081, 2016). "Previous work had shown that activated RAS in melanoma signals through CRAF, while normal signaling in healthy melanocytes is accomplished through BRAF." (PMID 26885666, 2016). "We demonstrated that, in BLM (BRAF-wild type, NRAS-mutant) melanoma cells, ERβ agonists [17β-estradiol, diarylpropionitrile (DPN), KB1] significantly inhibited cell proliferation, and this effect was abrogated by an ER antagonist." (PMID 27833586, 2016). "BRAF wild-type (WM1366 and MeWo) human melanoma cell lines were more resistant to ixazomib treatment with no significant decrease in cell proliferation from ixazomib with or without IFN-α treatment." (PMID 27783987, 2016). "MEK inhibitor significantly reduced ERK phosphorylation (pERK), as expected, in melanomas from all three patients, including BRAFV600E and BRAF wild-type melanomas." (PMID 27545456, 2016). "We also recently showed that in combination with either BRAF, ERK or MEK inhibition, ROCK inhibition delays melanoma growth." (PMID 27374095, 2016). "In the present study, we evaluated the effect of fisetin (which targets PI3K signaling) in combination with sorafenib, a multi-kinase inhibitor of mutant and wild-type BRAF and CRAF kinases, on melanoma cell invasion and metastasis." (PMID 26517521, 2016). "Single agent 48 hour treatment of IFN-α resulted in a minimal increase in apoptotic cell death in both BRAF V600E mutant (A375) and BRAF wild-type (WM1366) human melanoma tumor cells (4.9 ± 1.8 % and 12.5 ± 0.8%, respectively)." (PMID 27783987, 2016). "In this situation, RAS and MEK are elevated while tumor suppressors, such as PTEN, are decreased, and BRAF/MEK inhibitor (trametinib and cobimetinib) combinations are now accepted as the standard treatment for resistant melanomas." (PMID 27833586, 2016). "In sum, these results demonstrate that the combination of BRAF and BET inhibitors exert cooperative therapeutic effects against melanoma in vivo, resulting in significant tumor growth control and extended mice survival." (PMID 27169980, 2016). "Taken together, the in-vitro and in-vivo experiments indicated that co-targeting of MEK1/2 and PI3K/mTOR has improved anti-tumor activity compared to co-targeting of mutant BRAF and PI3K/mTOR even in melanoma cells with an intrinsic cross-resistant phenotype." (PMID 26678033, 2016). "In the treatment of advanced malignant melanoma, combined inhibition of BRAF and its downstream effector MAPK kinase (MEK) led to improved survival outcomes compared with BRAF inhibition alone." (PMID 27793177, 2016). "Finally, many melanomas do not express BRAF mutations but have high levels of ERK activation." (PMID 26871475, 2016). "During melanoma progression, EMT-inducing transcription factors (Snail1, Twist1, ZEB1 and Slug) are regulated by BRAF/MEK/ERK (MAPK) and PI3K signaling." (PMID 26517521, 2016). "We investigated the effect of BRAF-i and MEK-i on the expression of activating NK receptors/co-receptors that have been shown to play a major role in NK-mediated melanoma cell lysis (i.e. NKp46, NKp30, NKG2D and DNAM-1)." (PMID 27563819, 2016). "Combination treatment with ixazomib and IFN-α resulted in a significant, and synergistic, increase in apoptotic cell death in both the BRAF V600E mutant (A375) and the BRAF wild-type (WM1366) melanoma tumor cell lines." (PMID 27783987, 2016). "Collectively, these analyses support that the synergistic therapeutic potential of combined BRAF and BET inhibitors in melanoma results from distinct modulation of transcriptional programs controlling cell cycle, proliferation, and apoptosis." (PMID 27169980, 2016).
melanoma (continued). "We have evaluated these activities in the BRAF-dependent melanoma and provide evidence revealing a complex role for PERK in melanoma where a 50% reduction is permissive for BrafV600E-dependent transformation, while complete inhibition is tumor suppressive." (PMID 27977682, 2016). "MiR-146a was shown to be highly up-regulated by oncogenic BRAF and NRAS mutants frequently observed in melanomas." (PMID 26646588, 2016). "More recently, reovirus has also been shown to have enhanced activity when combined with BRAF and MEK inhibitors in melanoma." (PMID 27384486, 2016). "Moreover, mutant BRAF colon cancer cells are largely unresponsive to clinically available mutant BRAF inhibitors including vemurafenib and dabrafenib, although these inhibitors have achieved impressive clinical response rates in the treatment of patients with mutant BRAF melanomas." (PMID 27391062, 2016). "However, it was also possible that PN could elevate the MITF level because it is an inhibitor of NF-κB and the gene expression reciprocity between NF-κB and MITF was reported in melanoma cell lines as modulating intrinsic sensitivity of melanomas to inhibitors of the BRAF/MEK/ERK pathway." (PMID 26824319, 2016). "The effect of RT3D and RT combination therapy was assessed in multiple melanoma cell lines of various genetic backgrounds, including V600EBRAF mutant, Ras (K- and N-) mutant and BRAF/Ras wild-type (WT)." (PMID 27384486, 2016). "This led to the development and eventual FDA approval of the BRAF inhibitor vemurafenib/PLX4032 and dabrafenib/GSK2118436 for patients with advanced melanoma." (PMID 27648299, 2016). "MiR-524-5p was shown to directly bind to the 3′-UTR of both BRAF and ERK2 and to suppress the expression of these proteins in melanoma cells." (PMID 26646588, 2016). "BRAF also cooperates with the PI3K/AKT/mTOR (PI3K) signaling pathway, enhancing melanoma cell invasion and metastasis." (PMID 26517521, 2016). "This suggested a link between MEK and the transcriptional co-suppressor SKI, and indeed BRAF or MEK inhibition reduced SKI protein and mRNA levels in melanoma cells." (PMID 26977879, 2016). "This mitochondrial control of ER stress-mediated cell death is similar in both BRAF- and NRAS-mutant melanoma cells exposed to MEK inhibitors." (PMID 27250023, 2016). "Sequential inhibition of BRAF and downstream MEK is an active area of lung cancer research after encouraging results were seen in melanoma patients." (PMID 27938382, 2016). "Although targeting mutant BRAF kinase and inhibiting the downstream mitogen-activated protein kinase (MAPK) pathway produces high response rates in melanoma patients, the duration of responses is brief, highlighting the need for additional therapies." (PMID 27959922, 2016). "Anti-VISTA monotherapy reduced tumor growth in multiple pre-clinical models, B16OVA melanoma, B16-BL6 melanoma, MB49 bladder carcinoma, and PTEN/BRAF inducible melanoma." (PMID 28031817, 2016). "In this study, we analysed the effect of OP-A on A375 (BRAF V600E) and CHL-1 (BRAF wt) human melanoma cell lines, as compared to the HaCaT immortalised keratinocytes cell line." (PMID 27936075, 2016). "In the present study we characterized the OP-A effects on A375 (BRAF V600E) and CHL-1 (BRAF wt) melanoma derived cell lines, as compared to the HaCaT (immortalised keratinocytes) cell line." (PMID 27936075, 2016). "In conclusion, these findings should be confirmed by other studies which could highlight the role of IHC to detect BRAF V600E expression in patients at the time of progression, and to better clarify the meaning of the intensity of positive immunohistochemical expression in melanoma patients." (PMID 27863476, 2016). "In vitro, we found a striking upregulation of proapoptotic proteins in melanoma cell lines treated with combined BET and BRAF inhibitors, compared to any single‐agent treatment." (PMID 27169980, 2016).
melanoma (continued). "Moreover, all lipoplexes could effectively internalize into melanoma UACC-903 cells, although the highest internalization and localization in the cytoplasm, associated to a significant reduction of BRAF protein expression, was achieved with the optimized formulation." (PMID 28335259, 2016). "We next tested the ability of Rapamycin to co-operate with NVPBEZ235, in suppressing the growth of two established human melanoma cell lines in culture, WM1361 that like the zebrafish model harbour oncogenic RAS and A375 harbouring mutant BRAF." (PMID 27248171, 2016). "When investigating the therapeutic potential of combining inhibitors of mutant BRAF and TGFBR1, we noted that unexpectedly, low-dose PLX-4720 (a vemurafenib analogue) promoted proliferation of drug-naïve melanoma cells." (PMID 27835901, 2016). "Interestingly, the melanoma cell culture Me_cc135, with intermediate cross-resistance, was isolated from a specimen of a patient who subsequently (4.4 months after Me_cc135 isolation) was treated with a BRAF inhibitor and underwent progressive disease after two cycles of therapy." (PMID 26678033, 2016). "Moreover the high frequency of mutations in melanoma and the relative lack of effective therapies suggested that inhibition of BRAF activity may be an important new strategy in the treatment of some cancer types." (PMID 27713912, 2016). "Here, we show that RhoA, BRAF and Mitogen Activating Protein Kinase pathways are involved in the positive transcriptional regulation of CD70 expression in melanomas." (PMID 26828592, 2016). "Single agent treatment with BRAF inhibitors such as vemurafenib and dabrafenib have demonstrated improved survival for patients with V600EBRAF mutant melanoma and are currently approved by the US Food and Drug Administration for treatment." (PMID 26139106, 2015). "Besides causing apoptosis and cell cycle arrest in BRAFV600E mutant melanoma cells, in BRAF wild type cells PLX4032 has also been shown to have the paradoxical effect of activating the MAPK pathway through the transactivation of CRAF by a partially blocked wild-type CRAF-BRAF dimer." (PMID 25939769, 2015). "A comparative semiquantitative pattern of positive staining was also observed both in normal cells adjacent to the melanoma cells, but also in specimens of MMR-proficient/BRAF mutant colorectal cancer cells, serving as controls." (PMID 25695059, 2015). "The introduction of BRAF and MEK inhibitors into clinical practice has improved outcomes for patients with metastatic BRAF-mutant melanoma." (PMID 26137449, 2015). "Activation of STAT3 serine-727 and tyrosine-705 phosphorylations is promoted by BRAF(V600E) activity, whereas MEK inhibition decreases STAT3 phosphorylation in NRAS-mutant melanoma." (PMID 26116372, 2015). "In this study we performed the molecular appraisal of BRAF, NRAS, CKIT and EGFR genes altogether in a highly selected cohort of melanoma patients with lung metastases, that had been surgically treated with curative intent." (PMID 26305188, 2015). "Of note, BRAF inhibitors, which are routinely used in the clinic for the treatment of patients with BRAFV600E positive melanomas, have been reported to suppress PGC-1α expression." (PMID 26000250, 2015). "Our findings reveal that BRAF inhibition activates a c-Jun/RHOB/AKT pathway that promotes tumor cell survival and further support a role of this pathway in the resistance of melanoma to vemurafenib." (PMID 26098773, 2015). "The use of BRAF and MEK inhibitors in stratified patients has led to significant successes in the targeted therapy of melanoma, but the development of resistance is creating a major challenge." (PMID 25818589, 2015). "Two cell lines with focal ETV1 amplification demonstrated ETV1 dependency in melanoma proliferation, and ETV1 co-expression with oncogenic mutant NRAS or BRAF demonstrated enhanced proliferation." (PMID 26158900, 2015).